PPARG (peroxisome proliferator activated receptor gamma)
Diseases named in the same sentence as PPARG in open-access papers (continued):
Sharing a sentence is not in itself a finding about the gene and the disease.
Obesity (continued). "In adipose tissue, SIRT1 inhibits PPARγ activity, promotes lipolysis, and reduces fat storage, which is essential for the prevention of obesity and metabolic syndrome." (PMID 39199358, 2024). "These compounds are known for their anti-obesogenic properties, making them a promising candidate for downregulating PPARG related to obesity." (PMID 39409084, 2024). "In summary, we identified 18 bioactive compounds from Nelumbo nucifera leaves with potential anti-obesity effects, focusing on their interactions with the PPARG protein." (PMID 39744140, 2024). "In this study, we thoroughly investigated the potential of small molecules extracted from the thunder god vine (Tripterygium wilfordii) for obesity treatment, with a particular focus on their activating effects on PPARG and inhibitory effects on PTGS2." (PMID 39684213, 2024). "Against this background, the expression of key pro‐inflammatory factors, Leptin and TNF‐α and anti‐inflammatory proteins namely PPARγ and adiponectin in the adipose can be manipulated in favour of obesity reduction." (PMID 39698791, 2024). "Previous research has found associations with variants tied to obesity and diabetes, including SNPs in KCNQ1, PPARG, and GNB312–19." (PMID 38854080, 2024). "These compounds demonstrated superior binding affinity and specificity toward two key obesity targets, PPARG and PTGS2, suggesting their potential to regulate fat metabolism and mitigate inflammatory responses." (PMID 39684213, 2024). "For instance, the PPARG can regulate systemic insulin resistance, PPARG dysregulation will cause obesity, and HSP90AA1 can inhibit the reduction of adipogenesis through the in vivo pathway to trigger the anti-obesity effect." (PMID 38674532, 2024). "In contrast, miR-130 was found to be downregulated in obesity modulating 5 lncRNAs, as well as a player in PPARγ cell signaling." (PMID 38668382, 2024). "In the context of obesity, PPARγ facilitates adipose-tissue formation, while PPARα and PPAR-β/δ influence lipid metabolism and metabolic health." (PMID 39766314, 2024). "The pharmacological activation of peroxisome proliferator‐activated receptor gamma (PPARγ) is a convenient and promising strategy for promoting beige adipocyte biogenesis to combat obesity‐related metabolic disorders." (PMID 38988496, 2024). "Ellagic acid exerts anti-obesity effects through multiple mechanisms, including inhibition of adipogenesis (PPARG gene), de novo lipogenesis, and pancreatic lipase activity." (PMID 39409084, 2024). "Increased levels of the polyunsaturated fatty acid Arachidonic acid increased the expression of both Pparγ and Obr, suggesting one possibility of Obr expression increase in diet‐induced obesity." (PMID 38704700, 2024). "As mentioned, PPARγ is a promising anti-obesity target, with multiple PPARγ agonists currently under development." (PMID 39062047, 2024). "The proteins, mTOR, S6K, PPARγ, and C/EBPα, are considered to be essential for the treatment of obesity, and these are negatively regulated by AMPK." (PMID 38327997, 2024). "It has been well-documented that PPARγ plays a central role in adipogenesis and obesity-related complications." (PMID 37649895, 2023). "On the other hand, PPT ginsenosides have pharmacological effects on the central nervous and cardiovascular systems, and PPT reportedly acts as a PPARγ antagonist; thus, targeting PPARγ is considered a promising treatment option for obesity." (PMID 38139116, 2023). "Previously, it was shown that PPARγ expression at both mRNA and protein levels was reduced in the adipose tissue of mice and humans with obesity." (PMID 37299580, 2023). "According to recent studies, anti-obesity effects were proven through the expression of peroxisome proliferator-activated receptor gamma (PPAR-γ) and AMP-activated protein kinase (AMPK) in the skin of yuja, which is rich in unsaturated fatty acids." (PMID 37553478, 2023).
Obesity (continued). "NEDD8-based neddylation of PPARγ is crucial to conjugating and stabilizing PPARγ during adipogenesis and provides a potential anti-obesity therapeutic strategy that targets the neddylation of PPARγ." (PMID 37244925, 2023). "The right usage of PPARγ agonists and antagonists in those suffering from obesity with various conditions can aid scientists." (PMID 37513932, 2023). "FABP4 regulates adipogenesis by downregulating PPARγ and attenuates the development of diet-induced obesity in mice." (PMID 37244925, 2023). "Polymorphisms of the PPARG gene were associated with developing periodontitis together with T2DM, and with obesity, lipid, glycemic, and periodontal characteristics." (PMID 37047733, 2023). "Obesity occurs due to the abnormal regulation of adipogenesis, promoted by adipogenesis regulators such as PPARγ, C/EBPα, FAS, and CD36." (PMID 36838843, 2023). "In a mouse model of diet-induced obesity, abnormal adipose expansion was associated with a deregulated COX-2/PPARγ ratio, increased levels of proinflammatory markers, macrophage infiltration and tumor growth." (PMID 36670988, 2023). "As research continues, the types of miRNAs found that regulate the expression of PPARγ have increased, and their regulatory mechanisms are gradually explored, providing more selectivity for future applications such as obesity treatment." (PMID 36901991, 2023). "PPARγ, a central metabolic regulator and primary drug target combatting insulin resistance, is hyperacetylated in both aging and obesity." (PMID 37408258, 2023). "In the present study, EECM exerted anti-obesity effects in vitro and in vivo by suppressing the expression of PPARγ, C/EBPα, SREBP-1, and FAS and p-ACC expression via the AMPK pathway." (PMID 36771320, 2023). "However, both PPARG rs1801282 and rs3856806) are in linkage disequilibrium; rs1801282 is the most studied, and some work has associated this polymorphism with obesity or obesity-related traits, whereas rs3856806 has been associated with protective activity in dyslipidemia." (PMID 37761915, 2023). "Further, PPARG expression in immune cells and adipose tissue negatively correlate with obesity, demonstrating complex functions for this transcription factor in regulating body weight." (PMID 37051264, 2023). "Given the well-established relationship between visceral obesity and metabolic disease, this points to a unique relationship between BPS and obesity that is different from other PPARγ agonists such as those used medically." (PMID 37529602, 2023). "Because FABP4 negatively regulates PPARG at the posttranscriptional level and represses preadipocyte differentiation, lower expression of FABP4 has been associated with obesity in different studies." (PMID 37255997, 2023). "PPARγ activation by its agonist, pioglitazone, attenuated obesity-induced arterial stiffening and reduced the inflammatory and oxidative status of PVAT in ob/ob mice." (PMID 37627590, 2023). "In this study, we employed BZ26 to elucidate the molecular mechanisms that link obesity to cancer by understanding how modulating PPARγ activity affects the differentiation of mature adipocytes to CAAs." (PMID 37649895, 2023). "PPARγ acetylation regulates PPARγ activity, and the dynamics of acetylation are disturbed in obesity and aging." (PMID 37833942, 2023). "Dysfunctional PPARγ signaling leads to unregulated lipogenesis, which is a major contributor to the development of hepatic steatosis and obesity induced by a high-fat diet (HFD)." (PMID 37907845, 2023). "Our study showed that HFD led to the repression of PPARγ gene expression in both WT and KI animals, possibly due to obesity-induced DNA hypermethylation." (PMID 37189379, 2023). "In summary, SR1664 improved insulin sensitivity and reduced fibrosis in the HFHC diet, suggesting selective PPARγ modulation is effective in obesity-related liver fibrosis." (PMID 37886997, 2023).
Obesity (continued). "Altogether, our study strongly indicates that RE improves the lipid profile in animals before the onset of classical signs of obesity, perhaps associated with an increase in fasting GLP-1 or possibly through the upregulation of PPARα and PPARγ." (PMID 37755254, 2023). "The study had shown that Brd4 binds to the promoter and enhancer of GdF3 to promote PPARγ-dependent expression of GdF3 in macrophages and modulated lipid metabolism and diet-induced obesity." (PMID 36741233, 2023). "Several reports have demonstrated that olive leaves extract inhibits PPARγ and C/EBPα in vitro model and in high-fat diet-induced obesity." (PMID 36647430, 2023). "Exosomal miR-27a derived from adipocytes induces insulin resistance in C2C12 muscle cells through miR-27a-mediated repression of PPARγ and downstream genes involved in obesity." (PMID 36901991, 2023). "DNA methylation can alter the expression of obesity-associated genes, such as neuropeptide Y (NPY), peroxisome proliferator-activated receptor gamma (PPARγ), fatty acid binding protein 4 (FABP4), and sterol regulatory element-binding protein-1 (SREBP-1)." (PMID 37627544, 2023). "Collectively, adipocyte PPARγ acetylation renders systemic metabolism toward obesity, insulin resistance, and dyslipidemia during aging." (PMID 37408258, 2023). "In a mice model of obesity and diabetes, treatment with another PPARγ agonist, rosiglitazone, improved insulin sensitivity, increased serum adiponectin levels, and reduced inflammation in adipose tissues." (PMID 37627590, 2023). "For example, DNA methylation of the peroxisome proliferator-activated receptor gamma (PPARG) gene, which regulates adipocyte differentiation, has been shown to be associated with obesity and insulin resistance." (PMID 37445852, 2023). "Altogether, it seems that the expression level of SREBP1c, FAS, and ACC had a positive correlation with obesity indices as well as HOMA-IR while the expression level of PPARγ, C/EBPα, and LXR had an inverse correlation with adiposity indices in all subjects." (PMID 37106328, 2023). "Reports have indicated that deletion of PPARγ in AT of obese mice protected the mice against HFD-induced obesity and insulin resistance." (PMID 37649895, 2023). "PPARγ is indispensable in the process of adipocyte differentiation, and the phosphorylation level of PPARγ at Thr166 is positively correlated with obesity status." (PMID 37143582, 2023). "In line with this, a decreased expression of PPARγ, CEBPα, and LXRα in adipose tissue of women with obesity can reflect low adipose tissue expansion in the present study." (PMID 37106328, 2023). "In vivo injection of the autophagy inhibitor chloroquine in mice blocked high-fat diet-induced obesity and inhibited autophagy levels of 3T3-L1 preadipocytes in vitro which promoted proteasome-dependent degradation of PPARγ and weakened lipid differentiation." (PMID 38020065, 2023). "Recent studies have shown that certain synthetic and natural substances that inhibit PPARγ are effective in treating obesity." (PMID 37049636, 2023). "PPARγ deficiency in macrophages promotes the predominance of pro-inflammatory macrophages and the decrease of alternatively activated macrophages in adipose tissue in obesity, indicating that PPARγ is essential in controlling macrophage alternative activation." (PMID 37153549, 2023). "Thiazolidinediones are PPARγ full agonists with potent insulin-sensitizing effects, whereas their oral usage is restricted because of unwanted side effects, including obesity and cardiovascular risks." (PMID 36841479, 2023). "miR-27a induced insulin resistance in C2C12 skeletal muscle cells by inhibiting PPARγ and its downstream genes involved in the development of obesity." (PMID 37510277, 2023). "Our recent work revealed significant elevation in PPARγ acetylation levels in aging and obesity, in which SirT1 activity was diminished." (PMID 37408258, 2023).
Obesity (continued). "In fact, in silico analysis demonstrates that quercetin and rutin target PPARγ and thereby have potential anti-obesity effects." (PMID 36670988, 2023). "Serine 273 phosphorylation of PPARγ, which was shown to play a critical role in obesity and insulin resistance, is mediated by the Cdk5/ERK1/2 axis." (PMID 37047128, 2023). "AdipoRon’s main functions are through the activation of AMPK and PPARγ pathways in obesity-related disorders." (PMID 37240258, 2023). "As for the challenges and advancements of PPARγ agonism for the treatment of obesity and T2DM, they have been discussed in the previous section." (PMID 37435495, 2023). "Because of its critical role in these processes, PPARγ is regarded as acritical target for therapeutic intervention in obesity treatment." (PMID 37886153, 2023). "There is evidence that other HSPs, that is, HSP-A12A, regulate adipocyte differentiation and diet-induced obesity through positive feedback regulation with PPARγ (peroxisome proliferator-activated receptor gamma)." (PMID 36867437, 2023). "E3 ubiquitin ligase-mediated protein ubiquitination and proteasome-dependent degradation of PPARγ gradually exhibited clear mechanisms in the development of obesity." (PMID 37244925, 2023). "PPARγ acetylation in adipose tissue dynamically fluctuates in physiological diurnal rhythms and increases in pathological conditions of obesity, aging, and disruption of the circadian cycle." (PMID 36394167, 2023). "Meanwhile, another study revealed that the hypoxia inducible factor (HIF1α) signaling was enriched in FIPs suppressed PPARγ and negatively correlated with adipogenesis during diet-induced obesity." (PMID 37138165, 2023). "Peroxisome-proliferator-activated receptor gamma (PPARγ) has become increasingly appreciated as a knot connecting aging and obesity." (PMID 37408258, 2023). "Other studies have shown that cinnamyl alcohol can exert anti-obesity effects by inhibiting the increase in PPARγ expression." (PMID 35563944, 2022). "Namely, obesity in rats results in downregulation of PPARγ in the PFC, meanwhile chronic treatment with pioglitazone reversed depressive-like behaviors associated with obesity in CUMS mouse model." (PMID 35782423, 2022). "Another approach to obesity management is the regulation of the proximal proliferator-activated receptor-γ (PPARγ) expression." (PMID 35885378, 2022). "Next, we wanted to evaluate the mRNA abundance of SFRP5, WNT5A and PPARγ and their link with obesity, so we classified the cohort into NW subjects (control group) and MO patients." (PMID 36077270, 2022). "TZDs inhibit the Cdk5-mediated Ser273 phosphorylation of PPARγ in adipose tissue, which in turn, down-regulate expression of genes involved in obesity, including adipsin, a fat-cell-selective gene, and adiponectin, an insulin-sensitizing adipokine." (PMID 35769384, 2022). "Pharmacological PPARγ antagonists have already been shown to have anti-obesity and antidiabetic activity in preclinical models." (PMID 35436993, 2022). "To date, there are little data on the involvement of PPARG SNPs in the development of obesity in children, and reports on the implications of gene polymorphisms in the process and consequences of excessive weight gain are even scarcer in Romanian populations." (PMID 36466447, 2022). "Previous studies have reported the role of epigenetic modifications in the development of obesity through the regulation of PPARγ." (PMID 35397570, 2022). "Fundamentally different with orlistat, KY19334 suppress inflammation with the improvement of obesity by the Wisp1-mediated suppression of expression of the Pparγ and Cebpα9." (PMID 36450849, 2022). "We aimed to determine the correlation between the expression of PPARγ and the expression of miR-143 and miR-34a as possible modulators of PPARγ, which can be used in new obesity treatment." (PMID 35397570, 2022).
Obesity (continued). "PPARγ is considered the master activator of adipogenesis, and its inhibition is a preferred strategy to screen anti-obesity agents." (PMID 36501129, 2022). "The presence of mouse and rat models of obesity or lipodystrophy prompted us to explore the mechanism of the different response to TZDs by species and tissue-specific effects of PPARγ on NAFLD." (PMID 35013417, 2022). "PPARγ phosphorylation at Ser273 was demonstrated in obesity models and treatment with the PPARγ agonist dephosphorylates this residue in the adipose tissue." (PMID 36359851, 2022). "PPARγ plays a key regulatory role in the occurrence of obesity, glucose metabolism, atherosclerosis, lipid metabolism, apoptosis, and hypertension." (PMID 34969364, 2022). "PPARγ inhibitors were shown to be useful in treating obesity, through the inhibition of expression of the adipose tissue genes, but the drugs can have undesirable effects in other tissues." (PMID 36501129, 2022). "Our study showed that obesity can lead to decreased PPARγ expression in lung tissue and LPS intervention can aggravate this decrease in PPARγ expression." (PMID 36213491, 2022). "These miRNAs were suspected to target the molecules including STAT3, PI3K, AKT and FOXO1 in leptin signal in obesity, PPARγ and FOXO1 in adipogenesis pathway, and p38MAPK, PPARγ and PPARα in white adipose tissue browning pathway." (PMID 36065413, 2022). "Constitutive PPARγ deacetylation (K268R/K293R, 2KR) improves the metabolic phenotype of a mouse model of diet-induced obesity (DIO)." (PMID 37213714, 2022). "Further obesity-related genes include MC4R, peroxisome proliferator-activated receptor gamma (PPAR-G), and both adipokine-encoding genes (LEP and ADIPOQ)." (PMID 35565885, 2022). "There are studies in which the PPARG gene expression in the adipose tissue (both subcutaneous and visceral) increases with obesity, while in others it decreases, and there are studies in which no changes were observed." (PMID 36555437, 2022). "Nevertheless, the obesity-related biomarker, peroxisome proliferator-activated receptor-gamma (PPARγ), is a nuclear receptor protein that regulates fatty acid and glucose homeostasis." (PMID 35369101, 2022). "Nevertheless, the relationship between the PPARγ expression pattern in different adipose tissues and obesity is unclear." (PMID 35397570, 2022). "It has been widely acknowledged that reversing the obesity-related phosphorylation of PPARγ at Serine 273 (Ser273) improved insulin sensitivity." (PMID 36551260, 2022). "Previous studies have demonstrated the role of the PPARγ/PGC-1α pathway in inhibiting obesity, delaying the progression of chronic obstructive pulmonary disease, and attenuating pulmonary edema." (PMID 36213491, 2022). "Disruption of PPARγ in bone marrow cells impairs alternative macrophage activation, promoting these animals to develop diet-induced obesity, insulin resistance, and glucose intolerance." (PMID 35795675, 2022). "PPARγ is closely related to lipid disorders and obesity based on its fundamental role in lipid and glucose metabolism." (PMID 35846293, 2022). "Recently, RCAN2 was found to be a target gene of peroxisome proliferator-activated receptor gamma (PPARγ), which regulates hepatic lipid deposition in mice with diet-induced obesity." (PMID 35370729, 2022). "Berberine blocks food absorption, reduces body gain, and visceral adipose weight by decreasing the level of PPARγ in high-fat diet-induced obesity mice when the level of GATA-binding proteins 3 increases and downregulates the expression of PPARγ and PPARα." (PMID 36263142, 2022). "ATF4 knockout was found to protect against diet-induced obesity, hypertriglyceridemia, and hepatic steatosis by significantly decreasing the expression of lipogenic genes, such as PPARγ, SREBP-1c, and FASN." (PMID 34237916, 2022). "PPARγ has an inhibitor role in the incidence of non-alcoholic fatty liver disease, hyperlipidemia, and obesity." (PMID 35745155, 2022).